CXCR3 (C-X-C motif chemokine receptor 3)
Diseases named in the same sentence as CXCR3 in open-access papers (continued):
Sharing a sentence is not in itself a finding about the gene and the disease.
Hypertension (6 papers, 2018 to 2025). The presence of chronic increased pressure in the systemic arterial system. "According to the models built, both drugs were able to modulate common pathways through their common off-target binding, but ibrutinib modulated more strongly proteins involved in hypertension, such as CXCR3 and CFTR." (PMID 40744952, 2025). "An increased fraction of CD8+ T cells and elevated levels of CXCR3 chemokines in hypertensive patients’ circulation has been important to forge a link between T-cell-driven inflammation and hypertension." (PMID 35794867, 2022). "Studies have shown that adhesion molecules ICAM-1, VCAM-1, immune cells, chemokine CCL2, and CXCR3 are key factors in human hypertension; these series of events results in the progression of hypertension." (PMID 29573749, 2018). "We found that blockade NLRP3 therapy markedly reversed hypertension, in consistent with the results reported by Krishnan, as well as significantly reduced NLRP3 pathway protein expression, decreased PICs, CCL2, CXCR3, and VCAM-1, adjusted TH, GAD67, and GABA in PVN and plasma NE." (PMID 29573749, 2018).
lung adenocarcinoma (6 papers, 2013 to 2025). A carcinoma that arises from the lung and is characterized by the presence of malignant glandular epithelial cells. "Analysis of NSCLC data from The Cancer Genome Atlas (TCGA) identified a strong correlation (Spearman correlation coefficient >0.55) among the expression of CXCL9, CXCL10, and their cognate receptor (CXCR3) in both lung adenocarcinoma (LUAD) and lung squamous carcinoma (LUSC)." (PMID 38518770, 2024). "It has also been found that CXCR3 is expressed in lung adenocarcinoma cell lines, which suggests CCR7 and CXCR3 play a role in lung adenocarcinoma metastasis to lymph nodes." (PMID 39083441, 2025). "CXCR3 is also constitutively expressed in lung adenocarcinoma; however, CXCR3 expression is not significantly correlated with lymph node metastasis." (PMID 24259307, 2013).
lymphopenia (6 papers, 2014 to 2024). Reduction in the number of lymphocytes. "High levels of miR-34a-5p in naïve CD4+ T cells inhibit Th1 cell polarization by down-regulating CXCR3, leading to the diminished activation of cytotoxic T lymphocytes, natural killer cells, and natural killer T cells, as well as possible lymphopenia." (PMID 37509488, 2023). "Notably, reduced CXCR3 expression was consistent with lymphopenia, as suggested by reduced clinical absolute lymphocyte counts." (PMID 38690733, 2024). "Anti-CD3 treatment induced transient lymphopenia but spared circulating CXCR3+ T cells." (PMID 37458220, 2023).
metastatic melanoma (6 papers, 2011 to 2024). A melanoma that has spread from its primary site to another anatomic site. "CXCR3 expression on monocytes has been shown to promote lung metastasis in a mouse model of metastatic melanoma, and like PD-L1, is induced by interferon signaling." (PMID 35493454, 2022). "In metastatic melanoma, CXCR3 expression on tumour-reactive CD8+ cells was positively correlated with survival." (PMID 24961933, 2014). "In addition, chemokine receptor CXCR3, the CXCL10 receptor, was shown to be overexpressed in brain metastatic melanoma cells, and silencing either CXCR3 or CXCL10 can efficiently reduce migration toward astrocytes." (PMID 37190188, 2023). "As such, we could detect expressions of CCR5, CCR9 and CXCR3 in all malignant metastatic melanoma cells, using a immunohistochemistry protocol described previously." (PMID 21179030, 2011). "A phase I/II clinical trial, investigating tebentafusp (a bispecific fusion protein targeting gp100) in metastatic melanoma patients reported an increase in serum CXCL10 and reduction in circulating CXCR3+ CD8+ T cells." (PMID 37170733, 2023). "While intratumoral CXCL10 was identified as a potential favorable prognostic factor in metastatic melanoma, circulating CXCL10 has also been reported to have dual effects and cell growth as well as angiogenesis in cancer, depending on CXCR3 expression and other factors in the TME." (PMID 38236249, 2024).
myocarditis (6 papers, 2012 to 2025). Myocarditis is a condition that is characterized by inflammation of the heart muscle (myocardium). "CXCL9 mRNA expression directly correlated with the intensity of myocarditis, as well as with mRNA expression of CXCR3, CCR4, CCR5, CCR7, CCR8 and their ligands." (PMID 23150742, 2012). "In this study, inhibition of CXCR3 attenuated T-cell infiltration into the myocardium via inhibiting T-cell migration toward macrophages, showing the vital role of the T-cell–macrophage cross-talk in myocarditis development." (PMID 39023770, 2025). "As for myocarditis, the expansion of CXCL9/10+CCR2+ macrophages and CXCR3hi CD8+ T lymphocytes is linked to the pathogenesis of ICI‐associated myocarditis, highlighting the therapeutic potential of CXCR3 pathway modulation." (PMID 40787068, 2025). "Notably, recent preclinical studies have shown that β-arrestin-biased inhibitors such as ACT-777991 can specifically block the infiltration of CXCR3+ CD8+ T cells into the heart, significantly improving survival rates in models of immune checkpoint inhibitor-induced myocarditis." (PMID 40786052, 2025). "Independent studies have shown that the CXCL10/CXCR3 axis plays an extremely important immunomodulatory role in ischemic heart disease, myocarditis, leukoplakia, nonischemic heart failure, and KD, thus modulation of this axis is a potential immunotherapy target for these diseases." (PMID 33188570, 2021).
nephritis (6 papers, 2014 to 2023). Inflammation of renal tissue. "Mice that lack CXCR3 in Tregs specifically displayed an aggravated course of the experimental nephritis, that correlated with reduced Treg recruitment to the kidney and an overwhelming Th1 immune response." (PMID 36993956, 2023). "Future studies are aimed at investigating the impact of CPT on nephritis by inhibiting Fli-1 modulation of the CXCL10/CXCR3 axis." (PMID 37790939, 2023). "CXCR3−/− MRL/lpr mice showed amelioration of nephritis with reduced glomerular tissue damage and decreased albuminuria, which may be owed to impaired trafficking of effector T cells to injured kidney." (PMID 32089645, 2020). "Although the roles of CCR6 and CXCR3 in the recruitment of Tregs into the kidney have already been established in similar antibody-mediated nephritis models, CCR4 in Tregs during the late phase has not been investigated." (PMID 32917984, 2021). "Taken together, reduced expression of CXCR3 in kidneys and spleens of DFO-fed NZBWF1 mice observed here might reflect decreased populations of activated T and/or B cells that mediate autoimmune sequelae and nephritis observed in this model." (PMID 24945254, 2014). "Similarly, lack of CXCR3 also reduces renal T cell infiltrates and nephritis after induction of nephrotoxic serum nephritis in non-autoimmune C57BL/6 mice." (PMID 24945254, 2014).
neuroblastoma (6 papers, 2016 to 2025). Neuroblastoma (NB) is the most common solid, extracranial childhood tumor. "With the exception of ID2, all the other immune genes (CD8a, IL2, IL7R, IL6, ID3, and CXCR3) were also highly expressed in low-risk neuroblastoma patients further confirming the significance of these immune genes in neuroblastoma cases with favorable outcomes." (PMID 36068918, 2023). "High expression levels of CCL2, CCL4, CCL21, CD200, CXCR3, and IGSF6 were significantly associated with improved survival in neuroblastoma patients (all p < 0.001)." (PMID 40718780, 2025). "In our study, we identified four chemokines, CCL2, CCL4, CCL21, and CXCR3, in neuroblastoma samples, which may originate from different cellular subsets." (PMID 40718780, 2025). "Six characteristic genes (BATF, CXCR3, GIMAP5, GPR18, ISG20, and IGHM) were identified by machine learning, and these genes are associated with multiple immune-related pathways and immune cells in neuroblastoma." (PMID 39559348, 2024). "BATF, CXCR3, GIMAP5, GPR18, IGHM have lower expression in high-risk neuroblastoma patients." (PMID 39559348, 2024). "Our study demonstrates that tertiary lymphoid structure (TLS)-related genes play a crucial role in neuroblastoma (NB) prognosis, with a 6-gene TLS signature (CCL2, CCL4, CCL21, CD200, CXCR3, and IGSF6) serving as a promising prognostic biomarker for NB." (PMID 40718780, 2025). "TGF-β1 produced by neuroblastoma cell lines was shown to upregulate the surface expression of CXCR4 and CXCR3 on both CD56high and CD56low NK cells, while it downregulated CX3CR1 in the CD56low subset." (PMID 27766097, 2016). "Similarly, neuroblastoma cells have been shown to upregulate CXCR4 and CXCR3 on both CD56dim and CD56bright NK cells and to reduce CX3CR1 (which is important for NK cell extravasation) on CD56dim NK cells viarelease of TGF-β." (PMID 32272610, 2020). "Finally, neuroblastoma cells have been shown to upregulate CXCR4 and CXCR3 and reduce CX3CR1 expression on NK cells via the release of TGF-β." (PMID 32272610, 2020). "BATF, CXCR3, GIMAP5, GPR18, ISG20, and IGHM may serve as biomarkers that reflect the conditions of the immune microenvironment of neuroblastoma and hold promise in guiding neuroblastoma treatment." (PMID 39559348, 2024).
ovarian tumor (6 papers, 2018 to 2021). "In the current study, we demonstrated delayed tumour metastasis and increased survival with associated increases in CD8+ T-cell activation, proliferation and CXCR3-mediated T-cell recruitment to ovarian tumour tissue." (PMID 33513866, 2021). "The expression level of CXCR4 in ovarian tumor tissues was significantly higher than that of CXCR3." (PMID 33829065, 2021). "We also identified increased expression of the CXCL10 receptor, CXCR3, on CD8+ T cells in the peritoneal cavity, and increased CXCR3+ expression in ovarian tumour sections following sitagliptin treatment." (PMID 33513866, 2021). "The mRNA expression levels of CXCR3 and CXCR4 in ovarian tumor tissues were significantly higher than those in normal ovarian tissues." (PMID 33829065, 2021). "CXCL10 is secreted by cancer cells in vitro in response to inflammatory stimuli; and in “immunoreactive” ovarian tumours, with increased relative expression of CXCL10 and CXCR3, there is increased recruitment of T-lymphocytes and subsequent positive impact on survival." (PMID 34200333, 2021). "As for CXCR7, CXCL11 was also significantly elevated in ovarian tumor stroma compared with normal sections, while stromal CXCR3 expression was not, emphasizing a selective contribution of the CXCR7/CXCL11 axis." (PMID 30051594, 2018).
systemic sclerosis (6 papers, 2018 to 2024). A chronic disorder, possibly autoimmune, marked by excessive production of collagen which results in hardening and thickening of body tissues. "Furthermore, anti-CXCR3 antibody levels predict the deterioration of lung function in systemic sclerosis patients, while anti-CXCR3 antibodies predict cardiovascular risk in patients with cardiovascular diseases." (PMID 39768675, 2024). "Importantly, autoantibodies against the extracellular N-terminal region of CXCR3 were associated with a better prognosis for systemic sclerosis." (PMID 37047169, 2023). "Those complexes, which are present in blood and tissues from patients suffering from systemic sclerosis (SSc), are DNA-size-dependent and activate plasmacytoid dendritic cells in a TLR9-dependent but CXCR3-independent manner." (PMID 37446102, 2023). "It was reported that chemokine receptors CXCR3 and CXCR4 related to lung function damage in patients with systemic sclerosis." (PMID 32582168, 2020). "The involvement of CXCR3 and CXCR4 has already been discussed in the pathogenesis of systemic sclerosis." (PMID 29566745, 2018). "The chemokine receptors CXCR3 and CXCR4 are involved in the pathogenesis of fibrosis, a key feature of systemic sclerosis (SSc)." (PMID 29566745, 2018).
acute GVHD (5 papers, 2012 to 2025). "Adoptively transferring CXCR3‐expressing Tregs can significantly ameliorate acute GVHD in the liver, lung, and small intestines." (PMID 34919342, 2021). "The expression of receptors of chemokines, such as C-C chemokine receptor type 5 (CCR5) and CXC chemokine receptor 3 (CXCR3), on antigen-specific Treg support a role for proper trafficking of Treg to target tissue in the prevention of acute GVHD in murine models." (PMID 22587383, 2012). "Compared to the use of CCR5 or CXCR3 antagonists alone, the combined blockade of these two chemokine receptor antagonists more effectively reduced the incidence of acute GVHD and alleviated the clinical manifestations of acute GVHD in mice." (PMID 39840040, 2024).
autoimmune hepatitis (5 papers, 2014 to 2017). Hepatitis caused by autoantibodies. "Regulatory T cell homing to the site of liver inflammation is crucial for the success of Treg therapies, thus we examined the crucial liver‐homing chemokine receptor, CXCR3, on blood Treg of autoimmune liver disease patients." (PMID 28176332, 2017). "Infusion of autologous ex vivo expanded CXCR3+ Tregs could be an effective therapeutic approach for the treatment of patients with autoimmune hepatitis." (PMID 26106627, 2015). "This hypothesis is supported by the fact that in a mouse model of autoimmune hepatitis, adoptive transfer of CXCR3+ Tregs can induce tolerance and ameliorate the disease." (PMID 25415223, 2014). "Peripheral Treg from PSC and PBC patients also showed no change in their CXCR3 expression with sustained culture in VLDP, thus VLDP therapy may be applicable for all three autoimmune liver diseases without impairing the recruitment capacity of Treg." (PMID 28176332, 2017).
bladder cancer (5 papers, 2015 to 2024). "TADCs produced high levels of CXCL9 that increased PD-L1 expression in bladder cancer T24 cells by activating the CXCR3-related signaling." (PMID 33407095, 2021). "In this study, we found that CXCL9 secreted by TADCs enhanced PD-L1 expression in bladder cancer T24 cells, which was abrogated by the CXCR3 antagonist AMG487." (PMID 33407095, 2021). "Therefore, CXCR3 pathway activation can be used as a predictive biomarker to guide bladder cancer patients before receiving immunotherapy." (PMID 35562800, 2022). "Given that anti-PD-1 and anti-PD-L1 are promising to treat some types of solid cancers the CXCL9/CXCR3/PD-L1 axis may be new therapeutic targets for intervention of bladder cancers." (PMID 33407095, 2021). "The results showed that in bladder cancer, FLT3LG not only exhibited significant positive correlations with immune checkpoints (CTLA416, IDO117), cytokines and chemokines (TNFSF13B, TNFRSF14, CXCR3, CCL4) but also exhibited the closest association with genes related to HLA18." (PMID 38213738, 2024). "Hence, STAT3 activation is crucial for inducing PD-L1 expression in tumor cells and inhibition of STAT3 activity may inhibit the CXCL9/CXCR3 signaling-induced PD-L1 expression, benefiting bladder cancer patients." (PMID 33407095, 2021). "Therefore, our findings suggest that the CXCL9/CXCR3/PD-L1 axis may be the potential therapeutic targets for bladder cancer." (PMID 33407095, 2021). "Such novel findings indicated that bladder cancer cells enhanced CXCL9 in TADCs, which significantly up-regulated PD-L1 expression in cancer cells by activating the CXCR3-related STAT3/Akt signaling." (PMID 33407095, 2021). "Demographics and the number of CXCR3-positive, CD3-positive, CD20-positive and CD138-positive cells were not different between controls associated with bladder cancer and those without." (PMID 27339056, 2016).
chronic hepatitis B (5 papers, 2014 to 2026). "CXCR3-associated chemokines might contribute to liver inflammation in chronic hepatitis B, while MCP-3 and G-CSF were inhibited by HBV infection." (PMID 24976843, 2014). "Granzyme-B+ Trm were found to be enriched during CXCR3+ chronic hepatitis B infection, antagonizing tolerance and adding to liver damage." (PMID 37056783, 2023). "To further evaluate the role of CXCR3 and CCL5 in the course of chronic hepatitis B and their potential for future treatment, we analyzed single-cell RNA sequencing data from the public database GSE247322, examining the expression of CXCR3 and CCL5 in PBMCs of CHB patients with high viral load." (PMID 41258710, 2026).
encephalitis (5 papers, 2014 to 2022). An acute inflammatory process affecting the brain parenchyma. "The authors found that TNF-α produced during WNV encephalitis caused specific downregulation of CXCR3 expression on infected and bystander neurons." (PMID 25324719, 2014). "On the other hand, CCR5 seems to be functional and active alongside CXCR3 in WNV-encephalitis model." (PMID 26906062, 2016). "In viral encephalitis, the role of CXCR3 and CCR5 has been studied mainly in animal models and shows differences depending on virus type and strain virulence." (PMID 26906062, 2016). "Thus, we anticipate that the blockade of CXCR3 during flavivirus induced encephalitis may promote pathogenesis." (PMID 25324719, 2014). "On one hand, mice deficient in CXCR3 succumb faster to HSV-2 infection; on the other hand, HSV-1-infected mice lacking CXCR3 are protected from fatal encephalitis, indicating a mouse strain and tissue-specific role of CXCR3." (PMID 33492607, 2021). "Thus, the dual blockade of CXCR3 and CCR2 is necessary to achieve a survival benefit during lethal SFV-induced encephalitis." (PMID 25324719, 2014).
fibrosis (5 papers, 2012 to 2024). the formation of excess fibrous connective tissue in an organ or tissue in a reparative or reactive process. "We found that the inflammatory cytokine CXCL10 and its receptor CXCR3 in the liver were strongly associated with fibrosis." (PMID 32898182, 2020). "While treatment with LXA4 reduced CXCL10 expression 2.39 times in comparison to fibrosis group, CXCR3 expression decreased 2.35 times." (PMID 35307625, 2022). "For the exponentiated regression coefficient, (e.g. for liver CXCR3 with coefficient of 1.16): one unit increase in liver CXCR3 results in (1.16–1) x 100 = 16% percentage change in Fibrosis (TE)." (PMID 32898182, 2020). "Surprisingly, the opposite was true as we found a significantly higher frequency of CXCR3(+)CD56Bright NK cells in livers of patients with F3/4 fibrosis as compared to livers with less advanced fibrosis." (PMID 22792160, 2012). "However, the proportion of CXCR3+ eTregs was lower in the HF+++ group (37.4 ± 5.9%) than in patients with milder fibrosis (HF+/- and HF++, as compared to HF+++) (51.7 ± 2%; p = 0.009) and was not affected by SplM." (PMID 26731721, 2016).
graft versus host disease (5 papers, 2015 to 2022). An immune system disorder that occurs after allogeneic hematopoietic stem cell transplant and is a reaction of donor immune cells against host tissues. "CXCR3-chemokine ligand interactions have important roles in inflammatory, autoimmune, feto-maternal immune tolerance, transplant rejection, and graft-versus-host disease." (PMID 35281025, 2022). "Long-term administration of neutralizing anti-CXCR3 antibodies prevents alloreactive T cell-mediated graft-versus-host disease in a mouse model." (PMID 25866451, 2015).
lung disease (5 papers, 2004 to 2021). "A number of studies have shown that CXCL10 and its receptor CXCR3 are involved in the regulation of inflammatory, angiogenic and fibrotic processes also in human lung diseases." (PMID 27428020, 2016). "By contrast, lung disease in MRLlpr mice involves the recruitment of CXCR3 positive T cells via local secretion of CXCL10, and the endothelial expression of selectins and intercellular adhesion molecule (ICAM)-1." (PMID 21637713, 2011).